PAK6 (p21 (RAC1) activated kinase 6)
Description:
Serine/threonine protein kinase that plays a role in the regulation of gene transcription. The kinase activity is induced by various effectors including AR or MAP2K6/MAPKK6. Phosphorylates the DNA-binding domain of androgen receptor/AR and thereby inhibits AR-mediated transcription. Also inhibits ESR1-mediated transcription. May play a role in cytoskeleton regulation by interacting with IQGAP1. May protect cells from apoptosis through phosphorylation of BAD.
Synonyms: PAK5; BUB1B-PAK6
Tractability: Small molecule: a structure with a bound ligand is known; a high-quality ligand is known; it belongs to a druggable protein family. PROTAC: ubiquitination databases record sites on it; its protein half-life has been measured; a small molecule that binds it is known.
Target class: Protein Kinase; STE protein kinase PAKB subfamily; STE protein kinase STE20 family; STE protein kinase group; Enzyme; Kinase
Chemical probes: GNE-2861, PF-03758309
Gene: Protein-coding gene on chromosome 15 (40,217,428 to 40,277,489, forward strand). Ensembl gene ENSG00000137843.
Subcellular location: Cytoplasm; Nucleus
Subcellular location (Human Protein Atlas): Nucleoli fibrillar center; Nucleoplasm; Cell Junctions
Pathways (Reactome):
Signal Transduction: CDC42 GTPase cycle; RAC1 GTPase cycle; RHOD GTPase cycle; RHOH GTPase cycle; RHOV GTPase cycle
Developmental Biology: Activation of RAC1
Gene Ontology:
Molecular function: cadherin binding; protein binding; protein serine/threonine kinase activity; ATP binding; protein kinase activity; protein serine kinase activity
Biological process: apoptotic process; cellular response to starvation; cytoskeleton organization; regulation of DNA-templated transcription; regulation of MAPK cascade
Cellular component: fibrillar center; nucleoplasm; cytoplasm; cytosol; nucleus; postsynaptic density
Genetic constraint (gnomAD): Loss-of-function variants: 33 observed, 61.69 expected, observed/expected ratio (o/e) 0.53, 90% interval 0.4 to 0.71. The upper end of that interval is the gene's LOEUF score, 0.71, which puts it in group 2 of 6, group 1 being the genes least tolerant of losing a copy. Missense variants: 845 observed, 923.22 expected, observed/expected ratio (o/e) 0.92, 90% interval 0.86 to 0.97. Synonymous variants: 404 observed, 386.66 expected, observed/expected ratio (o/e) 1.04, 90% interval 0.96 to 1.13.
Homologues: Orthologues: chimpanzee PAK6 (99% identical), macaque PAK6 (99% identical), pig PAK6 (95% identical), guinea pig PAK6 (94% identical), rabbit PAK6 (93% identical), rat Pak6 (93% identical), mouse Pak6 (93% identical), dog PAK6 (87% identical), tropical clawed frog pak6 (65% identical), zebrafish pak6a (53% identical), zebrafish pak6b (49% identical). Paralogues in human: PAK5 (46% identical), PAK4 (45% identical), PAK3 (29% identical), PAK1 (28% identical), PAK2 (28% identical), MAP3K19 (21% identical), MAP3K1 (20% identical), MAP4K3 (17% identical), MAP4K5 (17% identical), MINK1 (16% identical), NRK (16% identical), STK3 (16% identical), and 23 more.
Diseases named in the same sentence as PAK6 in open-access papers:
PAK6 is named in the same sentence as 51 diseases in open-access papers, as found by Europe PMC text mining. Sharing a sentence is not in itself a finding about the gene and the disease. The quoted sentences say what the papers report.
prostate carcinoma (20 papers, 2007 to 2025). A carcinoma that arises from epithelial cells of the prostate gland. "HGF-induced cell-cell dissociation has been linked to PAK6 activation in prostate cancer DU145 and colon cancer HT29 cells." (PMID 28475121, 2017). "Moreover, PAK6 has been found to be associated with radiosensitivity and chemosensitivity in prostate cancer, chronic myeloid leukemia, and colon cancer, indicating the important role of PAK6 in cancer treatment response." (PMID 35902562, 2022). "PAK6 has also been linked to radiosensitivity of prostate cancer cells." (PMID 27542207, 2016). "p-21 activated 6 (PAK6), first identified as interacting with the androgen receptor (AR), is over-expressed in multiple cancer tissues and has been linked to the progression of prostate cancer, however little is known about PAK6 function in the absence of AR signaling." (PMID 24352566, 2014). "P21 upregulation in response to PAK6 knockdown also contradicts previous findings in prostate cancer cells, where PAK6 knockdown induced expression of cyclin D1, a proliferation marker negatively regulated by p21, enhancing tumor growth in vitro and in vivo." (PMID 40650306, 2025). "High PAK6 mRNA expression has been observed in lung cancer, colon cancer, ovarian cancer and prostate cancer." (PMID 39233332, 2024). "Previous studies have indicated that abnormal expression of PAK6 played critical roles in numerous types of cancers, including cervical cancer, prostate cancer, gastric cancer and liver cancer." (PMID 39696440, 2024). "The combination of a PAK6 inhibitor and docetaxel significantly reduced the viability of prostate cancer cells." (PMID 39233332, 2024). "Of note, PAK6 expression is upregulated in a number of cancers and PAK6 interaction with androgen receptor (AR) promotes its phosphorylation and prostate cancer cell motility and invasion." (PMID 39419978, 2024). "Downregulation of PAK6 by siRNA induced cell cycle arrest and inhibits cell growth in prostate cancer." (PMID 39233332, 2024). "In a study from 2010 on prostate cancer, PAK6 depletion also enhanced cellular radiosensitivity, suggesting an effect of this protein on therapy resistance." (PMID 35883575, 2022). "The knockdown of PAK6 inhibits the growth of prostate cancer growth and enhances the chemosensitivity to docetaxel of prostate cancer cells." (PMID 36230657, 2022). "PAK6 is overexpressed in prostate cancer, localizes to cell–cell adhesion, and drives epithelial colony escape based on its kinase activity." (PMID 36230657, 2022). "The PAK6 gene is overexpressed in prostate cancer, hepatocellular carcinoma, cervical cancer, and colon cancer." (PMID 34113558, 2021). "Dramatically, it was found that prostate cancer tissues had apparently higher PAK6 and ANT2 expression, but had dramatically lower SIRT4 expression, when compared to paired adjacent non-neoplastic tissues." (PMID 32194820, 2020). "Based on the depletion of PAK6, the level of apoptosis in prostate cancer cells was recovered following the overexpression of ANT2." (PMID 32194820, 2020). "A study revealed that PAK6 is highly expressed in a variety of malignant tumors, including prostate cancer, colon cancer, ovarian cancer and lung cancer." (PMID 32194820, 2020). "Meanwhile, PAK6 directly phosphorylates ANT2 at T107 to inhibit the apoptosis of prostate cancer cells." (PMID 32194820, 2020). "The correlation of the PAK6-SIRT4-ANT2 complex in prostate cancer was investigated, and the expression levels of PAK6, SIRT4 and ANT2 were evaluated in prostate cancer." (PMID 32194820, 2020). "In order to further investigate the correlation between PAK6 and the mitochondria of prostate cancer cells, CWR22RV1 and PC3 cells were used as a model system in the subsequent studies." (PMID 32194820, 2020). "For example, in prostate cancer LNCaP cells, PAK6 localizes in the nucleus 16, thereby inhibiting AR-mediated transcription." (PMID 32194820, 2020).
prostate carcinoma (continued). "In order to investigate the role of PAK6 in prostate cancer cells, the effect of PAK6 on the subcellular structure of prostate cancer cell CWR22RV1 was initially observed using transmission electron microscopy." (PMID 32194820, 2020). "The present study demonstrates that silencing PAK6 or ANT2 can induce apoptosis in prostate cancer cells." (PMID 32194820, 2020). "The expression of PAK6 in prostate cancer tissues is significantly higher than that of normal prostate tissues, especially after desperation." (PMID 32194820, 2020). "PAK6 was identified as a putative IQGAP1 binding protein and its expression has been linked to prostate cancer invasiveness." (PMID 28475121, 2017). "In prostate cancer, chemo-sensitivity to docetaxel was enhanced when used in combination with PAK6 siRNA." (PMID 27542207, 2016). "PAK6 inhibition, in combination with irradiation results in significant decrease in prostate cancer cell survival." (PMID 27542207, 2016). "Though previous reports have shown the overexpression of PAK6 in multiple cancers including prostate cancer, breast cancer and in hepatocellular carcinoma, there are limited studies investigating the signaling mechanism of PAK6 in cancer." (PMID 27542207, 2016). "The extent of PAK6 up-regulation inversely correlated with degree of miR-23a down-regulation (R2 = 0.69, P < 0.05), suggesting that the inhibitory effects of miR-23a on PAK6 were clinically relevant in prostate cancer." (PMID 25714010, 2015). "In this study, we found that the relationship between PAK6 overexpression and miR-23a levels in prostate cancer tissues was negatively correlated." (PMID 25714010, 2015). "Knockdown of PAK6 expression results in the inhibition of prostate cancer growth and enhanced chemosensitivity to docetaxel." (PMID 25426562, 2015). "When combined with irradiation, inhibition of PAK6 results in significantly decreased prostate cancer cell survival." (PMID 25426562, 2015). "Our previous study showed that PAK6 is up-regulated in prostate cancer and that the knockdown of p21-activated kinase 6 inhibits prostate cancer cell migration." (PMID 25714010, 2015). "PAK6 has been reported to be an important tumor suppressor in prostate cancer cells based on its ability to phosphorylate the androgen receptor, tumorigenic E3 ligase murine double minute-2 (Mdm2), and β-catenin." (PMID 25714010, 2015). "In agreement with our cell based studies, PAK6 expression was lower in prostate cancer (p = 0.003, fold change = -1.350)." (PMID 25248616, 2014). "The role of PAK6 in prostate cancer is very context dependent, with evidence suggesting that PAK6 can either promote or suppress prostate cancer." (PMID 25248616, 2014). "We report here that PAK6 is specifically required for carcinoma cell–cell dissociation downstream of hepatocyte growth factor (HGF) for both DU145 prostate cancer and HT29 colon cancer cells." (PMID 24352566, 2014). "Our results demonstrate that androgen-stimulated PAK6 activation is mediated through a direct interaction between AR and PAK6 and PAK6 activation promotes prostate cancer cells motility and invasion." (PMID 24130878, 2013). "In the present study, we demonstrate that androgen stimulation acts as an extracellular signal that activates PAK6 in an AR-dependent manner in prostate cancer LAPC4 and LNCap cells." (PMID 24130878, 2013). "We demonstrated that androgen stimulation acts as an extracellular signal that activates PAK6 in an androgen receptor-dependent manner in prostate cancer LAPC4 and LNCap cells." (PMID 24130878, 2013). "The androgen-stimulated activation of PAK6 is accompanied by increased prostate cancer cell motility and invasion." (PMID 24130878, 2013). "In current study, we present evidence linking androgen and PAK6 activation to prostate cancer cell motility and invasion." (PMID 24130878, 2013). "In prostate cancer cell lines, PAK6 expression is detected at higher levels in PC3, LAPC4, DU145 cells but not in LNCap cells." (PMID 24130878, 2013).
prostate carcinoma (continued). "In contrast to our previous study, where we established PAK6 as an oncogene targeted by the miR-185 tumor suppressor, this study suggests that PAK6 may have tumor-suppressive functions in prostate cancer." (PMID 40650306, 2025). "The deep deletions observed in PAK5 and PAK6, particularly in pancreatic and prostate cancers, point to the possibility that these isoforms may act as tumor suppressors." (PMID 39756822, 2025). "PAK6 expression in prostate cancer is even increased when androgen deprivation therapy fails." (PMID 39233332, 2024). "PAK6 has been well established as an important regulated protein in different types of cancer such as gastric cancer, hepatocellular carcinoma, cervical cancer, prostate cancer." (PMID 37789280, 2023). "In the recent years, PAK6 has been identified as oncogenic protein in different types of cancers like colorectal cancer, hepatocellular carcinoma, cervical cancer, prostate cancer, and gastric cancer." (PMID 35902562, 2022). "PAK6 can also directly regulate prostate cancer cell metastasis through LIMK1." (PMID 36230657, 2022). "However, when ANT2 was knocked down, the level of apoptosis did not recover after PAK6 overexpression, suggesting that PAK6 affects the apoptosis of prostate cancer cells through ANT2." (PMID 32194820, 2020). "In addition, studies have shown that PAK6 is positively correlated with the malignant degree of prostate cancer and preoperative prostate-specific antigen (PSA) levels." (PMID 32194820, 2020). "Although the effects of PAK6 on many malignancies, especially in prostate cancer, have been studied for a long time, the role of PAK6 in mitochondria remains unknown." (PMID 32194820, 2020). "Therefore, the study of the regulation mechanism of PAK6 has implications for the treatment of prostate cancer." (PMID 32194820, 2020). "PAK6 is known to be upregulated in hepatocellular carcinoma and prostate cancer." (PMID 27542207, 2016). "PAK6 is known to be overexpressed in hepatocellular carcinoma and prostate cancers." (PMID 27542207, 2016). "To determine whether PAK6 was involved in the miR-23a-mediated inhibition of migration and invasion in prostate cancer cells, we transfected PC-3 cells with siRNA-PAK6 (siPAK6)." (PMID 25714010, 2015). "MiR-23a suppressed prostate cancer migration and invasion by directly targeting PAK6." (PMID 25714010, 2015). "PAK6 expression has been linked to prostate cancer invasiveness but no mechanism has been identified; thus a functional role for PAK6 expression outside of androgen signaling remains to be elucidated." (PMID 24352566, 2014). "Furthermore, androgen-stimulation promoted prostate cancer cell motility and invasion were demonstrated in LNCap cells ectopically expressing PAK6-WT." (PMID 24130878, 2013). "Consequently, androgen-stimulated PAK6 activation promotes prostate cancer cell motility and invasion." (PMID 24130878, 2013). "This suggests a potential role of PAK6 in prostate cancer metastatic progression." (PMID 24130878, 2013). "We also find that a melanoma-associated mutation within the pseudosubstrate sequence, P52L, disrupts PAK6 autoinhibition enhancing its kinase activity, potentially correlating with increased expression of PAK6 in prostate cancer, and implied alterations in kinase activity." (PMID 24204982, 2013). "Additionally, further investigation revealed that PAK6 could phosphorylate AR, leading to AR degradation and cell death in prostate cancer." (PMID 39233332, 2024). "Others have previously shown that PAK6 phosphorylates MDM2 at the Ser186 and Thr158 sites, activating MDM2 to ubiquitinate the androgen receptor and inhibit tumor growth in prostate cancer cells." (PMID 40650306, 2025). "PAK6 phosphorylates ANT2 and promotes ANT2 protein degradation, thereby inhibiting prostate cancer cell apoptosis." (PMID 36230657, 2022).
prostate carcinoma (continued). "In the experiment, PAK6 or ANT2 was silenced, and activated caspase 3 and 9, and PARP significantly increased, suggesting that the apoptosis increased in prostate cancer cells." (PMID 32194820, 2020). "At the same time, in support of these present discoveries, it was also found that PAK6 and ANT2 are highly expressed, and that SIRT4 is lowly expressed in 9/12 frozen clinical prostate cancer tissues." (PMID 32194820, 2020). "Consistently, these clinical prostate cancer tissue evaluations reveal that PAK6 is positively correlated with ANT2 expression, but negatively correlated with SIRT4." (PMID 32194820, 2020). "These present findings provide insights into the new mechanism of PAK6 in the mitochondria, indicating that ANT2 and its phosphorylation and de-acetylation may play a critical role in the apoptosis of prostate cancer." (PMID 32194820, 2020). "Additional analyses revealed that miR-23a directly targeted the p21-activated kinase 6 (PAK6) gene to suppress the phosphorylation of LIM kinase 1 (LIMK1), resulting in cytoskeletal reorganization, and ultimately, the inhibition of prostate cancer cell invasion and metastasis." (PMID 25714010, 2015). "However, the regulation of ANT2 acetylation by PAK6 is independent of glutamine, which suggests that a high expression of PAK6 can maintain the protein stability and acetylation of ANT2 in the absence of glutamine, providing conditions for the survival of prostate cancer with the lack of glutamine." (PMID 32194820, 2020).
hepatocellular carcinoma (11 papers, 2015 to 2025). A malignant tumor that arises from hepatocytes. "Moreover, PAK6 regulates proliferation and progression in hepatocellular carcinoma (HCC) by negatively regulating KSP expression." (PMID 41009541, 2025). "In addition, PAK6 expression has been found to be decreased in renal cell carcinoma, but increased in hepatocellular carcinoma; PAK6 expression is also thought to be a potentially useful marker for the differentiation of human uterine cervical adenocarcinoma from squamous cell carcinoma." (PMID 25426562, 2015). "Nevertheless, the deep deletions observed for PAK5 and PAK6 in cancers such as pancreatic and prostate raise the possibility that these isoforms may function as tumor suppressors in certain contexts as has been suggested in hepatocellular carcinoma, a hypothesis that warrants further investigation." (PMID 39756822, 2025). "PAK6, a homologous protein of PAK1, was shown to be epigenetically regulated by the PRC2 complex in hepatocellular carcinoma." (PMID 36478132, 2023).
breast carcinoma (9 papers, 2015 to 2025). "Since PAK5 and PAK6 proteins are less frequently associated with breast cancer, our focus for this study was PAK4, but further investigation is warranted." (PMID 28198380, 2017). "This aligns with PAK6’s documented role in chemoresistance pathways, where overexpression confers resistance to oxaliplatin in colorectal cancer and 5-FU in breast cancer." (PMID 40708824, 2025). "Using an anti-PAK6 antibody that recognizes the native PAK6 protein, we investigated the subcellular localization of PAK6 in different cell types, including mouse embryonic fibroblasts (MEFs), breast cancer MCF7 cells and HEK293T cells." (PMID 39419978, 2024). "However, we have not tested the effects of KPT-9274 on the other group II PAK family members, PAK5 and PAK6, in breast cancer cells." (PMID 28198380, 2017). "While immunohistochemical staining of PAK1 in breast cancer patient specimens was correlated to tamoxifen resistance, possibly related to PAK1-mediated phosphorylation of ERα, PAK6 binds ERα and inhibits its transcriptional activity, and this PAK6-ERα interaction could be enhanced by tamoxifen." (PMID 26554417, 2015).